LINC02188 (long independently transcribed non-coding RNA 2188)
Gene: Long non-coding RNA gene on chromosome 16 (86,710,122 to 86,761,490, forward strand). Ensembl gene ENSG00000261175.
Diseases named in the same sentence as LINC02188 in open-access papers:
LINC02188 is named in the same sentence as 2 diseases in open-access papers, as found by Europe PMC text mining. Sharing a sentence is not in itself a finding about the gene and the disease. The quoted sentences say what the papers report.
breast carcinoma (1 paper, 2024). "Among these, four ncRNAs (CASC8, GRIK1-AS1, LINC02188, and ROCR) exhibit diminished expression levels in breast cancer, while one lncRNA (LINC00511) displays elevated expression in breast cancer." (PMID 38408075, 2024).
tumor (1 paper, 2022). "The expression of LINC02257, LINC02188, MYOSLID, C6orf223, MYG1-AS1, and Lnc-SKA2-1 was upregulated in tumor samples, while the expression of LINC00702, LOC100129434, and LINC01915 was downregulated in tumor samples." (PMID 35846431, 2022).